DPP4 (dipeptidyl peptidase 4)
Diseases named in the same sentence as DPP4 in open-access papers (continued):
Sharing a sentence is not in itself a finding about the gene and the disease.
Obesity (continued). "Considering the pivotal role of DPP4 and inflammation in the development of IR, we deduced that miR-214 might also be associated with obesity-induced IR." (PMID 32093712, 2020). "Since the direct regulatory effect of miR-214 on DPP4 was proved in our study, a hypothesis was conducted that miR-214 might play a key role in the disease progression of obesity-associated IR." (PMID 32093712, 2020). "As obesity is one of the most important risk factors for the pathogenesis of T2DM, it may be possible that adipose associated increase in plasma DPP4 plays an important role in linking obesity to T2DM." (PMID 31402899, 2019). "Recent studies indicated that DPP-4 inhibition attenuates obesity-associated inflammation." (PMID 28476142, 2017). "In this sense, it has been described that novel and relevant adipokines as visfatin and dipeptidyl peptidase 4 (DPP-4) are produced by white adipose tissue that might have great impact on cardiovascular complications associated with obesity." (PMID 27766104, 2016). "Therefore, the authors concluded that, at least in their studied group, DPP4 gene polymorphisms seem to be unrelated to the inter-individual risk of developing obesity-related metabolic complications." (PMID 26284071, 2015). "Many recent publications have linked DPP4 with the physiopathology of obesity." (PMID 25816202, 2015). "In mice, obesity and the associated visceral adipose tissue inflammation result in insulin resistance, a process that appears to be mediated via increased synthesis and release of hepatic DPP4, since eliminating hepatocyte DPP4 expression suppresses inflammation and improves insulin sensitivity." (PMID 33691757, 2021). "In mice, obesity and the associated visceral adipose tissue inflammation result in insulin resistance, a process which appears to be mediated via increased synthesis and release of hepatic DPP-4, since eliminating hepatocyte Dpp4 expression suppresses inflammation and improves insulin sensitivity." (PMID 30828317, 2019). "Since DPP4 is a key enzyme in incretin metabolism and inflammation, its inhibition represents a promising anti‐obesity strategy." (PMID 41510340, 2026). "Elevated DPP4 activity is frequently observed in obesity and contributes to impaired glucose tolerance, increased inflammation, and metabolic dysfunction." (PMID 41510340, 2026). "Our results are different from a previous study that reported administration of 80 mg/kg BW/day teneligliptin (DPP4 inhibitor) prevented obesity in mice given HFD for 10 weeks." (PMID 41510340, 2026). "Obesity was reported to stimulate the synthesis of hepatocytes and the secretion of DPP4, which act in conjunction with plasma factor Xa to promote inflammatory adipose tissue macrophages and insulin resistance." (PMID 40742315, 2025). "In our study, DPP-4 protein expression and enzymatic activity were significantly higher in OB+/DM+ compared with OB+/DM− subjects, consistent with previous reports describing increased DPP-4 expression and activity in obesity and T2DM." (PMID 41561152, 2025). "Dipeptidyl peptidase-IV (DPP4, also named CD26) is originally found to be highly expressed on adipocytes and hepatocytes due to elevated glucose levels and obesity." (PMID 40607249, 2025). "Circulating DPP4 levels are significantly increased in mice and humans in metabolic disease and obesity." (PMID 40771104, 2025). "Dipeptidyl peptidase-4 and sterol regulatory element binding proteins (SREBPs) contribute to obesity (DPP-4)." (PMID 40242447, 2025). "There is growing evidence that increased DPP-4 activity can potentially influence excessive fat deposition and metabolic dysfunction, which can result in the development of insulin resistance and obesity." (PMID 38339106, 2024). "In obesity, an over-activation of DPP-4 is observed, resulting in the accumulation of ROS and the production of proinflammatory cytokines." (PMID 38339106, 2024).
Obesity (continued). "In individuals with obesity, there is a correlation between high levels of DPP4 and several factors, including increased concentrations of macrophages in WAT, elevated levels of leptin and inflammatory cytokines, and reduced adiponectin concentrations." (PMID 39335642, 2024). "Overall, this study improved our understanding of the dynamic molecular basis of beige adipogenesis and the potential contribution of DPP4+ adipocyte lineages to the pathological expansion of WAT during diet-induced obesity." (PMID 39465352, 2024). "Plasma DPP4 activity increases with obesity, which has been postulated to contribute to reduced incretin activity in the setting of obesity and insulin resistance." (PMID 38961511, 2024). "In the current study, we report DPP4 was elevated 4-fold in Pemt–/– mice, which have both hepatomegaly and nonalcoholic steatohepatitis, demonstrating that in addition to obesity, liver-specific insults can induce the release of DPP4." (PMID 36472923, 2023). "Over the past 2 decades, several incretin-based therapies, including GLP-1 receptor agonists (RAs) and dipeptidyl peptidase-4 (DPP-4) inhibitors, have been developed and approved for the treatment of both T2D and obesity." (PMID 37703084, 2023). "Given its strong correlation with adipose tissue accumulation and obesity in both humans and mice, soluble, circulating DPP4 was initially characterized as an adipokine." (PMID 36472923, 2023). "Further analysis revealed that the increased levels of adipose tissue-derived miR-548ag after the onset of obesity upregulated the expression of DPP4 by suppressing DNMT3B in the liver, leading to abnormal glucose tolerance and decreased insulin sensitivity." (PMID 36769291, 2023). "Aging and obesity are also reported to induce impaired hematopoietic regeneration by promoting expansion of the adipogenic lineage which produces an excess of dipeptidyl peptidase 4 (DPP4)." (PMID 37928907, 2023). "Recently, it has been shown that the dipeptidyl peptidase-4 (DPP-4) enzyme is considered as adipokine secreted excessively in obesity." (PMID 36419097, 2022). "Increased DPP4 activity and/or concentration is considered to be a manager of several metabolic abnormalities, including obesity, non-alcoholic fatty liver, T2DM, and CAD." (PMID 35885620, 2022). "Sitagliptin, one of the DPP-4 inhibitors, has been shown to decrease MetS, obesity-induced adipose tissue inflammation, and fatty liver by regulating the adenosine monophosphate-activated protein kinase and adiponectin levels in obese mice." (PMID 35054972, 2022). "This further supports the idea that hepatocyte-secreted DPP4 is a major contributor to increased serum DPP4 activity during obesity." (PMID 35909571, 2022). "The overexpression of DPP4 in hepatocytes accelerates HFD-induced obesity and AT inflammation and liver steatosis." (PMID 35909571, 2022). "Animal models of complete DPP4 silencing demonstrate that the DPP4 contributes to the development of obesity and insulin resistance in the condition of chronic caloric excess and positive energy balance." (PMID 36140405, 2022). "Several studies have established that the DPP4 activity is altered in some conditions such as obesity, non-alcoholic fatty liver, T2DM, and CAD; however, data about the DPP4 concentrations are scarce and contradictory." (PMID 35885620, 2022). "In 2011, DPP-4 was proposed as a new adipokine involved in the link between adipose tissue, obesity, and metabolic syndrome." (PMID 35628332, 2022). "In this study, serum DPP4 concentrations were significantly higher in obese subjects than in lean subjects, and DPP4 release was strongly correlated with adipocyte size, suggesting that adipocytes are an important source of DPP4 in obesity." (PMID 35053615, 2022).
Obesity (continued). "The following keywords were used in different combinations for the literature search: obesity, adipokines, pathogenesis, leptin, resistin, visfatin, chemerin, DPP-4, adiponectin, omentin, isthmin, nesfatin, preparations, and clinical study." (PMID 36499312, 2022). "Obesity is a major risk factor for HCC and is typically accompanied by increased levels of serum DPP4." (PMID 35053615, 2022). "As confirmed by protein chip analyses, KY19334 decreased the expression levels of various adipokines such as angiopoietin‐3, DPP4, IGFBP‐5, leptin, resistin and PAI‐1, which are implicated in obesity‐related insulin resistance." (PMID 35384342, 2022). "This in combination with the facts that both obesity and fatty liver disease (even after adjustment to BMI) are known risk factors for severe COVID-19 disease makes it highly unlikely that the decrease in circulating DPP4 activity in severe COVID-19 could be explained by the higher BMI values." (PMID 35195023, 2022). "DPP-4 is an important marker of obesity and its complications, particularly diabetes mellitus, which is actively used as a target for therapy and the development of drugs that reduce blood glucose levels." (PMID 36499312, 2022). "Indeed, previous studies have showed that DPP4 was a novel adipokine released from immune cells, adipose cells, and bone marrow cells, which correspondingly indicated that sDPP4 concentrations and activity were linked to obesity, metabolic syndrome, T2D, and inflammatory diseases." (PMID 35586625, 2022). "DPP4 enzymatic activity was suggested to be upregulated in proinflammatory situations, including obesity, and it was reported to be significantly positively correlated with BMI19,32." (PMID 35332212, 2022). "Anagliptin (DPP4 inhibitor) ameliorated leptin resistance and attenuated food intake and body weight in diet-induced obesity mice." (PMID 35586625, 2022). "In fact, GLP-1 receptor agonists and DPP4 inhibitors are widely used classes of anti-diabetic and/or anti-obesity agents." (PMID 34072172, 2021). "Previous investigations demonstrated altered DPP4 activity/concentration in relation to metabolic diseases such as obesity and T2DM." (PMID 32852705, 2021). "Increased levels of circulating dipeptidyl peptidase-4 (DPP4), the enzyme that cleaves GLP-1 and GLP-2, has been demonstrated to be associated with both T2D and obesity." (PMID 34502047, 2021). "DPP4 plasma levels are related to several markers of obesity, such as BMI, waist circumference, plasma triglyceride levels, leptin concentration, and fat cell volume." (PMID 34178021, 2021). "DPP4 release has been shown to strongly correlate with adipocyte size, potentially representing an important source of DPP4 in obesity." (PMID 33796069, 2021). "Evidence suggests that obesity in mice stimulates hepatocytes to synthesize and secrete DPP4, in turn promoting inflammation of adipose tissue macrophages and insulin resistance." (PMID 33691757, 2021). "Plasma levels of DPP-4 and circulating DPP-4 activity both increase with obesity and this correlates with insulin resistance." (PMID 33692997, 2021). "Different morbidities, such as obesity, old age, and chronic obstructive pulmonary disease (COPD) are associated with severe COVID-19 symptoms, which, in general, are supra regulated by dipeptidyl peptidase-4 (DPP-4)." (PMID 33791232, 2021). "In our study, DPP4 activity was independently associated with the presence of NAFLD, after adjustment for potential cofounders such as obesity, metabolic disease and insulin resistance." (PMID 32852705, 2021). "Hepatic DPP4 secretion is elevated in obesity and IR while specific hepatic DPP4 deletion through a short hairpin RNA (shRNA) strategy diminished adipose tissue macrophage infiltration and IR." (PMID 33440821, 2021). "DPP4 is expressed in adipocytes, and in patients with obesity, its expression and activity are elevated." (PMID 34178021, 2021).
Obesity (continued). "Major strength of this study is the coexistence of data on plasma and tissue DPP4 in a large population of metabolically characterized individuals with different grade of obesity, metabolic impairment and NAFLD/NASH." (PMID 32852705, 2021). "As such, synthetic GLP-1/GCG co-agonists resistant to dipeptidyl peptidase-4 (DPP-4) proteolysis became an attractive target for anti-obesity treatments." (PMID 34566894, 2021). "Another study proved that the novel DPP-4 inhibitor teneligliptin prevents high-fat diet-induced obesity accompanied by increased energy expenditure in mice." (PMID 34446063, 2021). "Varin et al26 a confirmed these findings in Dpp4Hep−/− mice, which confirmed that the 40% increase in circulating DPP4 under high-fat diet feeding or obesity is hepatocyte-derived." (PMID 32231442, 2020). "Here, we highlight our current understanding of the complex biology of DPP4 at the intersection of inflammation, obesity, T2D, and NAFLD." (PMID 32231442, 2020). "Some DPP4 substrates with CV impact are upregulated in obesity and/or T2DM as well as in COVID-19 such as CXCL5/RANTES and BNP." (PMID 32848769, 2020). "In the context of obesity, there has been a growing interest in the role of DPP4 in adipose tissue biology since its discovery as a novel adipokine." (PMID 31402899, 2019). "Recently, authors demonstrated that obesity in mice stimulates hepatocytes to synthesize and secrete dipeptidyl peptidase 4 (DPP4), which acts with plasma factor Xa to inflame adipose tissue macrophages." (PMID 31861591, 2019). "Recent studies have also highlighted that DPP-4 inhibition attenuates obesity-related inflammation, atherosclerosis, and insulin resistance by regulating M1/M2 macrophage polarization." (PMID 30889182, 2019). "Obesity is tightly linked with the pathogenesis of insulin resistance and T2DM and augmented release of DPP4 from adipose tissue is associated with visceral obesity and insulin resistance." (PMID 31402899, 2019). "Vaspin belongs to family of newly discovered adipokines besides others such as retinol-binding protein 4 (RBP4), dipeptidyl peptidase 4 (DPP-4), bone morphogenetic protein (BMP)-4, BMP-7, and progranulin, recently implicated in various aspects of obesity." (PMID 31779136, 2019). "But obesity being an important risk factor for T2DM and DPP4 being an adipokine, the role of adipose derived DPP4 in the pathogenesis of T2DM still remain debatable." (PMID 31402899, 2019). "A recent study showed that obesity in mice stimulates hepatocytes to synthesize and secrete Dpp4, which promotes visceral adipose tissue inflammation and insulin resistance." (PMID 30824564, 2019). "Elevated DPP4 expression has been linked to insulin resistance in obesity and NAFLD, and DPP4 inhibitors are currently in clinical use as anti-diabetic drugs." (PMID 31664995, 2019). "To evaluate the relative contribution of plasma DPP4 in obesity and hyperglycemia, we divided the T2DM population into obese (n = 52) and non-obese (n = 71) sub-groups." (PMID 31402899, 2019). "Recent publications have shown that obesity promotes liver dpp4 production, and liver-specific dpp4 transgenic mice displayed an elevated systemic dpp4 activity and diminished GLP-1 levels." (PMID 31794591, 2019). "Chronic overnutrition with a WD resulted in obesity, insulin resistance, and elevated plasma DPP-4 activity as well as heart enlargement and dysfunction." (PMID 30116740, 2018). "In this review, we described the disturbed lipid metabolism and immune modulators of lipid metabolism in obesity such as SREBPs, DPP-4, and Nrf2." (PMID 30050954, 2018). "Our objective was to study the impact of the DPP-4 inhibitor vildagliptin on gut functions and the intestinal ecosystem in a murine model of obesity induced by a Western diet (WD)." (PMID 29797022, 2018). "Pre-clinical studies have demonstrated CV protective effects of DPP-4 inhibition in models of genetic and dietary induced obesity, as well as pressure overload." (PMID 29669555, 2018).
Obesity (continued). "While Dpp-4 KO mice are protected against obesity, DPP-4 inhibitors lack an effect on body weight in humans." (PMID 30186247, 2018). "In the present study, pharmacological inhibition of DPP-4 by linagliptin led to an increase of cardiac citrulline and creatine levels in mice with dietary obesity." (PMID 28771625, 2017). "We found that linagliptin, a DPP-4 inhibitor, suppressed capillary rarefaction in the hearts of mice with dietary obesity." (PMID 28771625, 2017). "In conclusion, pharmacological inhibition of DPP-4 suppressed capillary rarefaction and contributed to favorable remodeling of cardiac metabolism in mice with dietary obesity." (PMID 28771625, 2017). "In a murine model of dietary obesity, we found that a DPP-4 inhibitor (linagliptin) suppresses capillary rarefaction in cardiac tissue and promotes favorable metabolic remodeling, characterized by elevated levels of citrulline and creatine." (PMID 28771625, 2017). "We previously reported that linagliptin, a dipeptidyl peptidase-4 inhibitor, improved DD in Zucker Obese rats, a genetic model of obesity and hypertension." (PMID 28476142, 2017). "The results imply that in obesity-related hypoxia DPP4 is abundantly expressed, contributing to the reduction in insulin activity and thereby to the onset of insulin resistance in these subjects." (PMID 26881257, 2016). "Rodent models of obesity, exhibit higher kidney and plasma levels of DPP4 and lower levels of megalin in the brush border of the proximal tubule." (PMID 27213360, 2016). "In an aged, high-fat-diet-induced obesity mouse model, the survival rates were improved by chronic DPP4 inhibition." (PMID 26937254, 2016). "The same improved glucose tolerance with increased GLP-1 and leptin levels was found in DPP4-depleted Dark Agouti rats with diet-induced obesity." (PMID 26284071, 2015). "Pair feeding and indirect calorimetry studies indicate that reduced food intake and increased energy expenditure accounted for the resistance to high fat diet-induced obesity in the Dpp4−/− mice." (PMID 26441982, 2015). "In addition, bioactive molecules and hormones associated with obesity (such as leptin, angiotensinogen, aldosterone stimulating factor, dipeptidyl peptidase 4, and resistin) that could explain the metabolic effect of adipose tissue on glomerular hyperfiltration were not measured." (PMID 26495973, 2015). "Circulating DPP4 activity has been reported to be increased in patients with obesity and T2DM, positively correlating with HbA1c levels, degree of obesity, and measures of insulin resistance and inflammation." (PMID 26075284, 2015). "The actual study also revealed an association between the %Meth of this locus with plasma total-cholesterol in severe obesity, which suggests a link between the DPP4 gene and plasma lipid levels." (PMID 23379505, 2013). "Since obesity is correlated with a low grade systemic whole body inflammation, we tested inflammatory cytokines to influence DPP4 secretion from myotubes." (PMID 23637948, 2013). "Serum DPP-4 levels correlate with adipocyte size and adipocytes potentially represent an important source of DPP-4 in obesity, which impairs insulin signaling." (PMID 24188631, 2013). "Therefore, this study aims to investigate the effects of the BPL herbal beverage on BW, LI, body fat content (BFC) percentage, lipid profiles, leptin levels, and DPP4 activity in male rats with obesity." (PMID 41510340, 2026). "The inability of BPL herbal beverages to inhibit DPP4 activity may indicate that their anti‐obesity effects probably pass through other mechanisms, which inhibit TG absorption and leptin secretion." (PMID 41510340, 2026). "Another study indicated that oral administration of 250 mg/kg BW of Anogeissus latifolia extract could inhibit DPP4 activity in male rats with obesity and glucose intolerance." (PMID 41510340, 2026). "DPP4 is an adipokine that plays a key role in obesity-induced inflammation and insulin resistance." (PMID 40786865, 2025).